CXCL2 (C-X-C motif chemokine ligand 2)
Diseases named in the same sentence as CXCL2 in open-access papers (continued):
Sharing a sentence is not in itself a finding about the gene and the disease.
tumor (continued). "Moreover, the tumor cell-derived CXCL6, CXCL2, and CCL20, TAM-derived CXCL9/CXCL10, and the stromal cell-derived CXCL12 also contributed to the accumulation of tissue-resident CD103+CD8+TILs in the TME." (PMID 37024870, 2023). "Overexpression of CXCL2 in GBM is correlated with worse overall survival and tumor malignancy." (PMID 38069130, 2023). "Additionally, it was demonstrated that tumor derived exosomes carry RNA to the type II alveolar cells of the lung stimulating expression of CXCL1, CXCL2, CXCL5 and CXCL12, through engagement with the toll like three receptor (TLR3), which recruit neutrophils." (PMID 36910138, 2023). "By contrast, CXCL1, CXCL2, CCL2 and TGFB2 with defined pro-tumorigenic roles are more highly expressed by EA1 tumor cells at baseline and may antagonize anti-tumorigenic effects of CD8+ T cells that do infiltrate this model." (PMID 36739466, 2023). "Taken together, these results indicate that CXCL2 inhibits MCF-7 cell proliferation and may act as a tumor suppressor gene." (PMID 38021148, 2023). "With the aim to evaluate if the phenotype of VSSP-BMDMs could be affected by the tumor-derived factors, we cultured BMDMs in the presence of VSSP and CXCL2, mimicking the influence of the Ptenpc−/−; Trp53pc−/− TME." (PMID 37055829, 2023). "CXCL10, CXCL5, MMP1, CXCL12, CXCL11, CXCL2, STAT1, IL‐6 and TLR2 were hub genes, which may drive the homing of immune cells in tumours and promote immune cell differentiation." (PMID 36524848, 2023). "We screened top ten upregulated genes in chemokine signaling pathways and the top fifty up-regulated genes in all sequenced genes, and consistently found CXCL2 and its receptor CXCR2 were significantly upregulated in CCL20-modulated PMN-MDSCs and tumor cells, respectively." (PMID 36859354, 2023). "CXCL8 interacts with CXCL1 and CXCL2 to promote the secretion of multiple proinflammatory, angiogenic, and immunomodulatory factors (including MMP and VEGF) by neutrophils, thereby promoting tumor metastasis in patients with NSCLC." (PMID 36726839, 2023). "CXCL10, CXCL5, MMP1, CXCL12, CXCL11, CXCL2, STAT1, IL‐6 and TLR2 were hub genes in network and may promote or inhibit the homing or of immune cells in tumours and immune cell differentiation, bring intratumoral immune heterogeneity." (PMID 36524848, 2023). "Various cells in the TME, such as surviving tumor cells, damaged endothelial cells, tumor stromal cells, etc., can release numerous pro-inflammatory mediators, including arachidonic acid, cytokines such as MIP2 (CXCL2), IL6, IL- 1β, TNFα, complement system, etc.." (PMID 35645842, 2022). "Numerous previous studies have indicated that neutrophils accumulate in the tumor microenvironment or metastatic niche to promote tumor metastasis, and that alveolar ECs are able to recruit neutrophils by secreting CXCL1, CXCL2, CXCL5 and CXCL12 after tumor-derived exosomal RNA stimulation." (PMID 36612175, 2022). "Chemokines CXCL1, CXCL2, and CXCL8 are highly expressed in Cancer Cells and act on CXCR1 and CXCR2, which are highly expressed in Neutrophil chemotactic the activity of Neutrophils and promote the generation of tumor immune microenvironment." (PMID 36401283, 2022). "In addition to HEVs, chemokines secreted by tumor cells and other immune components, such as CXCL2, CXCL20, and CXCL13, promote the influx of B cells into the tumor." (PMID 35967441, 2022). "CXCL2 is a member of the CXC sub-chemokines, is mainly produced by activated macrophages, has a strong chemotactic effect on neutrophils, and is involved in promoting angiogenesis, tumor cell growth, etc.." (PMID 34542679, 2022). "Interestingly, we observed high concordance of immune analysis results for HELLS with CXCL2 and IL6, revealing for the first time a possible immunological effect of HELLS in tumor." (PMID 34982796, 2022).
tumor (continued). "Next, Xiantao tool also exhibited the low expression of CXCL2 in HCC tissues compared to normal liver tissues including non-cancerous patients or matched adjacent para-tumor tissues." (PMID 36276119, 2022). "In a mouse tumor model, it was shown that radiation therapy triggers the secretion of CXCL1, CXCL2, and CCL5, which leads to neutrophil recruitment to tumor sites; in turn, neutrophils generate ROS and suppress PI3K/AKT/SNAI1 signaling, inhibiting epithelial–mesenchymal transition." (PMID 36555469, 2022). "Furthermore, in triple-negative breast cancer (TNBC), CXCL1, CXCL2, and CXCL8 are all highly expressed, which is beneficial for tumor blood vessel formation." (PMID 36612163, 2022). "Furthermore, upregulation of Cxcr4 and Cxcl2, and H2-Aa by PTT+GC treatment indicates an increase in antigen presentation and pro-inflammatory functions of the tumor-infiltrating B cells." (PMID 34976205, 2022). "Although SNAIL affected EMT, the secretion of CXCL2 by mesenchymal tumour cells, rather than SNAIL, attracted macrophages." (PMID 35541899, 2022). "However, chemokines released by HCC (CXCL-2, CXCL8 and CCL25), in turn, increase the proportion of neutrophils in the TME, forming an immunosuppressive microenvironment and leading to tumour progression." (PMID 36291944, 2022). "The expression levels of CXCL2, CXCL10 and CXCL11 were related to tumor stage." (PMID 35181719, 2022). "CXCL2 is highly expressed in HCC, and engineered overexpression of the CXCR2L receptor (CXCR2) on GPC3-CAR-T cells was shown to enhance CAR-T infiltration and expansion at the tumour site in a xenogeneic HCC model." (PMID 35158772, 2022). "Only CCL19 and CXCL2 were not upregulated in tumors, nor was CXCL2 in tumor-adjacent tissue compared to normal mucosa." (PMID 34885960, 2021). "The non-paired analysis confirmed significantly higher CCL19 and significantly lower CCL4 and CXCL2 expression in tumor-adjacent tissue than in tumors, and a lack of difference in the case of CCL3." (PMID 34885960, 2021). "In addition, ablation of α-gustducin (Gnat3) in KrasG12D-expressing pancreas increases the levels of different chemokines, including CXCL1 and CXCL2, which lead to G-MDSC recruitment and altered MDSC gene expression in early neoplasia." (PMID 34439836, 2021). "Thus, we investigated the expression of VEGF and the alternative proangiogenic factors CXCL2 and IL8 amongst the matched tumor samples." (PMID 34681839, 2021). "Repeated doses of colonosphere-derived EVs into tumor-free mice also increased the number of neutrophils present in the bone marrow and circulation, as well as the primary tumor because cells in the colonospheres increased expression of the neutrophil-recruiting chemokines CXCL1 and CXCL2." (PMID 33946403, 2021). "Moreover, oxaliplatin treatment of tumor-bearing rats induced the expression of the SASP factors IL6, IL8, CXCL1, CXCL2, and MMP." (PMID 33922007, 2021). "On the other hand, CAFs promote the expression of PD-L1 in tumor cells by secreting CXCL2 and CXCL5, and macrophages upregulate PD-L1 expression through TGF-β–induced EMT, which plays a critical role in tumor immunosuppression and immune evasion." (PMID 34395525, 2021). "Based on qRT-PCR analysis, upregulation of Cxcr2 and Cxcl2 were detected in untreated tumor tissue compared to contralateral non-tumor tissue." (PMID 34681839, 2021). "Compared with HVJ-E combined with the control plasmid without CXCL2 cDNA, C/H significantly reduced tumor volume, indicating the need for CXCL2 cDNA." (PMID 33575480, 2021). "Interestingly, while the upregulation in tumors is markedly higher for CCL4 and CXCL2, the CCL2, CCL8 and CCL19 transcripts are relatively downregulated in tumors compared to tumor-adjacent tissue." (PMID 34885960, 2021). "CXCL2 and CXCL3 were differentially expressed at different tumor stages." (PMID 34269159, 2021).
tumor (continued). "CXCL1, CXCL2, and CXCL5 have been shown to recruit MDSCs to the pre-metastatic niche through the interaction with CXCR2; once in the pre-metastatic site, MDSCs favor tumor cell recruitment and seeding by secreting TNFα, TGFβ, IL-6, CCL2 and CXCL2." (PMID 32823961, 2020). "Furthermore, we identify recruitment of immunosuppressive Gr1+ myeloid cells via tumor cell expression of CXCL1, CXCL2, and CXCL8 (CXCR2 ligands) expression, which were substantially reduced with MEKi or CXCR2 blockade." (PMID 32634121, 2020). "Interestingly, tumor exosomal RNAs activate alveolar epithelial toll-like receptor 3 (TLR3) to induce chemokines (CXCL1, CXCL2, CXCL5, and CXCL12) that are critical for neutrophil recruitment and lung pre-metastatic niche formation." (PMID 33101283, 2020). "In this model, it was shown that ILC2s mediate antitumor activity either by producing cytokines relevant in tumor control (IL-5, IL-13, and GM-CSF) or by producing CXCR2 ligands (CXCL1 and CXCL2), which could induce the apoptosis of CXCR2+ tumor cells." (PMID 32063901, 2019). "CXCL1, CXCL2, and CXCL8 have known tumor-supportive functions." (PMID 30870978, 2019). "Secondly, NLRP12 downregulates hepatocyte-specific expression of cytokines such as IL-6 and TNFα which promote proliferation and tumor growth, and chemokines CXCL1, CXCL2 and CCL2, which enhance inflammatory cell infiltration and thereby augment inflammation in the tumor milieu." (PMID 30990169, 2019). "CXCL1, CXCL2, and CXCL5 promoted LLC tumor growth with an increase in concentration." (PMID 29541408, 2018). "Importantly, tumor cells themselves can promote neutrophil recruitment to the TME, and IL-8, or its murine functional homologs CXCL1 (KC) and CXCL2 (MIP-2), have been shown to attract neutrophils to the TME in preclinical models of Ras-driven cancer." (PMID 27348007, 2016). "It is surprising that inhibition of CXCL1, which is also a CXCR2 agonist similar to CXCL2, exerted no inhibitory effects on the tumor suppression and neutrophil infiltration induced by HVJ-E+poly I:C treatment." (PMID 27259252, 2016). "These neutrophils may be able to kill the tumor cells in the first 24 hours and provoke release of CXCL1 and CXCL2 from the surrounding tissue, helping T-cells traffic to the tumor site." (PMID 24949488, 2014). "Moreover, owing to the heterogeneity of the tumor microenvironment, the proposed combination strategies might only be effective in HCC with high CXCL2 expression, indicating the potential of CXCL2 as a predictive biomarker for patient stratification." (PMID 41114470, 2026). "However, there were also elevated cytokines from the Beads-FT-mA20T that could potentially contribute to the tumour-promoting responses, as represented by increased levels of CXCL16, CXCL2 and CCL17 (See Section 4)." (PMID 40361460, 2025). "In addition, the expression of several pro-inflammatory cytokines and chemokines such as IL-1β, IL-22, TNF-α, CXCL1, CXCL2, CCL17 and CCL20 were reduced in IL-38KO mice, suggesting that IL-38 promotes tumour growth and development in cSSC through promoting an inflammatory tumour environment." (PMID 40057603, 2025). "Overall, these findings demonstrate that ERO1α expression promotes tumor-suppressive microenvironment via recruitment and accumulation of PMN-MDSC cells mainly by facilitating proper protein folding of cytokines needed for recruitment of PMN-MDSC cells such as G-CSF, CXCL1 and CXCL2." (PMID 41226317, 2025). "However, there is no study confirming the promotion of tumor progression in PCa through CXCL2-mediated polarization of macrophages towards the M1 phenotype." (PMID 40367014, 2025). "Accordingly, we found that CXCL2+ CAFs may secrete complement C3 to interact with C1Q+ TAMs, mainly targeting the pro‐angiogenic gene VEGFA to maintain their M2‐like phenotype in chemoresistant tumours." (PMID 39422697, 2024).
tumor (continued). "Additionally, CXCL1 and CXCL2 have been shown to promote the resistance of HCC cells to sorafenib, whereas C-X-C motif chemokine receptor 2 inhibition induces reprogramming of the tumor immune environment that promotes immune checkpoint inhibition in MASH-HCC." (PMID 39621069, 2024). "Besides, CXCL2 and CXCL10-11 were related to the tumor stage." (PMID 35181719, 2022). "Besides, critical chemokine ligand family members (including CXCL1, CXCL2, CXCL5, CXCL8, and CXCL11), which involved in tumor growth regulation and metastasis and mediated the enrichment of CD8+ T cells into the TME, were upregulated in the high AI score subtype." (PMID 36245985, 2022). "Similarly, in lung adenocarcinoma, CXCL2 secretion by αSMA+ CAFs increases PD-L1 expression by tumor cells and αSMA+ CXCL5-secreting CAFs are positively correlated to PD-L1 expression by melanoma and colorectal carcinoma tumor cells." (PMID 36338519, 2022). "Similarly, CXCL2 expression levels in DLBCL patients were not statistically significant in tumor tissues and normal samples." (PMID 35181719, 2022). "Ddx5 was increased in the whole skin lesions of MC903- or IMQ-treated Cd93–/– mice compared with their wild-type counterparts, along with fewer plaques on the ears or dorsal skin and reduced expression of Il4, Il13, Ccl11, Ccl17 and Ccl22 or Cxcl1, Cxcl2, Ccl20, Il23, Il17a and Il36γ." (PMID 36271146, 2022). "However, the effect of CXCL2 on tumor development in a ferroptosis-dependent manner has not yet been reported." (PMID 34252149, 2021). "C/H was more effective for tumor suppression than pCY4B/H without CXCL2 cDNA." (PMID 33575480, 2021). "Altogether, our results suggest the occurrence of an intricate CXCL2/CXCL8-CXCR2 axis in the modulation of cisplatin sensitivity by OC cells, thus corroborating with an important role of TME and a potential autocrine effect of CXCL2/CXCL8 on CXCR2 expressed by tumor cells." (PMID 34038868, 2021). "In parallel, we showed that this antagonist led to a lower vessel density and decreased infiltration of microglia/macrophages with a consecutive tumor volume reduction using an immunocompetent GBM rodent model focusing on the CXCL2/CXCR2 signaling pathway due to lacking the IL8 expression in mice." (PMID 33807899, 2021). "However, CXCL1 was not detectable in 5 female and 14 male tumor tissues (19 patients in total), and CXCL2 was not quantifiable in tumor tissues of 3 female and 8 male patients (11 patients in total)." (PMID 34654834, 2021). "Due to this dramatic down-regulation in chemokine receptors’ expression on TANs, we hypothesized that the chemokines binding CXCR2 and CXCR4 (i.e., CXCL1/CXCL2 and CXCL12, respectively) could be responsible for the differential infiltration of NDN and LDN into the tumor." (PMID 34680231, 2021). "Furthermore, the C-X-C motif chemokine ligand (CXCL)-2, CXCL8 and CCL25 released by HCC cells can in turn increase the neutrophil ratio in the TME, forming an immunosuppressive microenvironment and leading to tumor progression." (PMID 35059434, 2021). "Interestingly, the interaction of MSC with tumor cells modifies their trophic properties through the release of various cytokines such as CXCL1, CXCL2, CXCL12 or IL-6 and metalloproteinases (MMPs) that can degrade the extracellular matrix and promote tumor migration." (PMID 33081024, 2020). "This study also showed that heparanase negative macrophages, in contrast to WT-macrophages, could not invade tumor tissue in response to CXCL2 and did not attenuate tumor growth." (PMID 31850210, 2019). "Among the validated miR-135a cellular targets, CXCL2 is an antimicrobial gene serving as a ligand for the G-protein couple receptor CCR4 that plays a role in diverse cellular functions, including immune surveillance, inflammatory response, tissue homeostasis, and tumor growth and metastasis." (PMID 30456659, 2019).
tumor (continued). "Moreover, YKL-40 was likely to promote tumor angiogenesis by interacting with syndecan-1 on endothelial cells as well as metastasis by stimulating production of pro-inflammatory and pro-invasive factors such as MMP-9, CCL2 and CXCL2." (PMID 28036271, 2017). "Tumor upregulated chemokines included the followings: CXCL5 (138 fold increase); CCL25 (70 fold increase); CXCL11 (26 fold increase); CXCL6 (20 fold increase); CXCL1 and CXCL10 (11 fold increase); CXCL3 (8 fold increase); and CXCL9, CXCL2, and CCL3L1 (6 fold increase)." (PMID 29088818, 2017). "In addition, the increased RNA and cytokine levels of CXCL1 and CXCL2 could be restored by ferrostatin-1 treatment, suggesting that cisplatin enhanced the expression levels of CXCL1 and CXCL2 expression via inducing ferroptosis of tumor cells." (PMID 35784745, 2022). "Moreover, the anti-CXCL2 antibody could not completely abolish the tumor suppression achieved by HVJ-E+poly I:C treatment." (PMID 27259252, 2016). "Thus, CXCL2 is not sufficient to achieve the anti-tumor activity observed with HVJ-E+poly I:C." (PMID 27259252, 2016). "Additionally, MPL could not induce CXCL2 expression and neutrophil infiltration to the tumor bed in a manner similar to poly I:C treatment." (PMID 27259252, 2016). "Consistent with this, we found all angiogenesis-related genes to be significantly upregulated in non-pCR patients, with VEGFA, CXCL8, CXCL2, CXCL3, and HBEGF identified as core drivers of tumor angiogenesis and immune escape." (PMID 41514936, 2026). "In contrast, the expression of genes such as CXCL12 (C-X-C motif chemokine ligand 2) and DST (dystonin) exhibited an increase in TR in most normal tissues compared to tumor samples." (PMID 39349823, 2024). "Consistently, the production and expression of the chemokines CXCL1 and CXCL2, but not CCL3 and CCL5, were significantly upregulated in serum and tumor-infiltrating neutrophils from Arnt−/− mice." (PMID 36859266, 2023). "Except for an inverse relation between CXCL2 and CCL19 in non-transformed tumor-adjacent tissue, all of the correlations between the chemokine genes were positive." (PMID 34885960, 2021). "The expression of CCL4 and CXCL2 from MIP chemokines was significantly, and CCL3 insignificantly, upregulated in tumors compared to tumor-adjacent non-transformed tissue by 1.4-fold, 2.0-fold, and 1.3-fold, respectively." (PMID 34885960, 2021). "Compared to normal tissue from non-cancer patients, the CCL3, CCL4 and CXCL2 expressions were upregulated in both tumor and tumor-adjacent tissue, while CCL19 was upregulated solely in tumor-adjacent tissue." (PMID 34885960, 2021). "The novel combination of HVJ-E and recombinant CXCL2 protein resulted in increased tumor suppression compared with HVJ-E alone, whereas CXCL2 protein without HVJ-E did not suppress tumor growth." (PMID 27259252, 2016). "Furthermore, compared with tumor-bearing WT mice, Mettl3-cKO mice indicated a significantly higher secretion of CCL2 in peritoneal lavage and peripheral blood and CXCL2 in only peritoneal lavage but not in peripheral blood." (PMID 37932814, 2023). "Like CXCL5, CXCL2 could be an ancestry-related chemokine; however, CCL23 is a novel chemokine that appeared to be independent of ancestry, and its role in tumor suppression warrants further investigation." (PMID 37698493, 2023). "In the present study, CXCL2 was also found to be significantly elevated in the co-culture system of M2 and HCC cells, as well as in tumor tissues as compared to the corresponding non-tumor normal tissues from HCC patients, indicating its possible crucial role in HCC development." (PMID 27117207, 2016). "Unlike S100A8/A9, the abundance of CXCL1, CXCL2, and CXCL5 chemokines in scaffolds neither increased following the infiltration of cancer-induced neutrophils in MNs after tumor inoculation nor decreased after systemic depletion of neutrophils in tumor-bearing mice." (PMID 37553342, 2023).